NCR3LG1 (natural killer cell cytotoxicity receptor 3 ligand 1)
Description:
Triggers NCR3-dependent natural killer cell activation.
Synonyms: B7-H6; B7H6; DKFZp686O24166
Tractability: Antibody: UniProt places it where antibodies can reach, with high confidence; its Gene Ontology location is reachable by antibodies, with high confidence; UniProt predicts a signal peptide or a membrane-spanning region. PROTAC: ubiquitination databases record sites on it.
Gene: Protein-coding gene on chromosome 11 (17,351,800 to 17,377,341, forward strand). Ensembl gene ENSG00000188211.
Subcellular location: Cell membrane
Pathways (Reactome):
Immune System: Immunoregulatory interactions between a Lymphoid and a non-Lymphoid cell
Gene Ontology:
Molecular function: protein binding; receptor ligand activity
Biological process: NK T cell activation; signal transduction
Cellular component: plasma membrane
Genetic constraint (gnomAD): Loss-of-function variants: 23 observed, 25.52 expected, observed/expected ratio (o/e) 0.9, 90% interval 0.65 to 1.28. The upper end of that interval is the gene's LOEUF score, 1.28, which puts it in group 5 of 6, group 1 being the genes least tolerant of losing a copy. Missense variants: 299 observed, 336.45 expected, observed/expected ratio (o/e) 0.89, 90% interval 0.81 to 0.98. Synonymous variants: 110 observed, 127.83 expected, observed/expected ratio (o/e) 0.86, 90% interval 0.74 to 1.01.
Homologues: Orthologues: chimpanzee NCR3LG1 (98% identical), dog NCR3LG1 (32% identical), rat Ncr3lg1 (26% identical). Paralogues in human: TAPBPL (13% identical), TAPBP (11% identical).
Diseases named in the same sentence as NCR3LG1 in open-access papers:
NCR3LG1 is named in the same sentence as 70 diseases in open-access papers, as found by Europe PMC text mining. Sharing a sentence is not in itself a finding about the gene and the disease. The quoted sentences say what the papers report.
ovarian carcinoma (19 papers, 2017 to 2024). A malignant neoplasm originating from the surface ovarian epithelium. "Ovarian cancer cells release a soluble form of B7-H6 (gene NCR3LG1, natural killer cell cytotoxicity receptor 3 ligand 1), the main ligand for NKp30 present on NK cells, leading to the loss of NKp30 expression on NK cells in the TME." (PMID 32937961, 2020).
breast cancer (16 papers, 2019 to 2025). A primary or metastatic malignant neoplasm involving the breast. "This SNP is also highly significantly associated with expression of NCR3LG1, KCNJ11, and SNORD14 genes with fragmentary and elusive data on association with breast cancer." (PMID 33334016, 2020). "MiR-93 has been implicated as a potential immune regulator in breast cancer cells through targeting programmed death-ligand 1 (PD-L1)/cluster of differentiation 274 (CD274), programmed Cell Death 1 Ligand 2 (PDCD1LG2), and natural killer cell cytotoxicity receptor 3 ligand 1 (NCR3LG1)." (PMID 33918859, 2021).
glioma (15 papers, 2017 to 2025). A benign or malignant brain and spinal cord tumor that arises from glial cells (astrocytes, oligodendrocytes, ependymal cells). "These immune check points Programmed death-ligand 1 (PDL-1), B7-H3 (CD276), and B7-H6 (NCR3LG1) have been associated with aggressiveness and poor prognosis in glioma patients." (PMID 37261362, 2023). "However, further analysis found that NCR3LG1 shows negative relationship with CD44 in glioma, which may be partially explained by the low expression in malignant glioma and positive glioma survival biomarker of NCR3LG1." (PMID 35187044, 2021).
gastric cancer (6 papers, 2020 to 2025). A primary or metastatic malignant neoplasm involving the stomach. "It was discovered that the expression of B7H6 gene (also known as NCR3LG1; natural killer cell cytotoxicity receptor 3 ligand 1) was elevated in gastric cancer." (PMID 39768254, 2024). "B7H6 (NCR3LG1), an immune checkpoint belonging to the B7 family, is significantly overexpressed in gastric cancer." (PMID 39768254, 2024).
chronic-myelogenous-leukemia (2 papers, 2022 to 2024). "NCR3LG1 functions to encode the ligand of the natural cytotoxicity receptor NKp30 and knockdown of NCR3LG1 protects against cell death in the human chronic-myelogenous-leukemia (CML) cell line." (PMID 36408192, 2022).
colorectal adenocarcinoma (2 papers, 2021 to 2022). The most common type of colorectal carcinoma. "By analyzing selected tumor types, as invasive breast cancer, colorectal adenocarcinoma and skin cutaneous melanoma, we observed that both ERBB2 and NCR3LG1 transcripts show a variable, heterogeneous and non-correlative expression for each individual patient." (PMID 35036073, 2021).
Myeloma (1 paper, 2024). "Myeloma cells with NLRC5 mutations and overexpression of selected genes including TNFRSF10D, NCR3LG1, ULBP1, PVR, and PCGF5 were sensitive to NK cells." (PMID 38410372, 2024). "Myeloma cells with TRAF3 and WHSC1 mutations and overexpression of TNFRSF10D, NCR3LG1, ULBP1, PVR, and PCGF5 were tolerance to NK cells." (PMID 38410372, 2024).
myopia (1 paper, 2019). "None of these facts make NCR3LG1 a particularly attractive candidate for myopia development however, and there are many other candidate genes in the region that, based on biological function, may be more likely to be causal genes." (PMID 30704416, 2019).
vitiligo (1 paper, 2021). Generalized well circumscribed patches of leukoderma that are generally distributed over symmetric body locations and is due to autoimmune destruction of melanocytes. "The upregulated genes in vitiligo lesional skin include markers of inflammation (such as MARCO, NLRP10, PTGS2, and IL36G), oxidative response genes (DUOXA2), and NK cell receptors (NCR3LG1), revealing presence of activated immune response in vitiligo lesions." (PMID 33815367, 2021).
tumor (135 papers, 2013 to 2026). "NCR3LG1 is tumor overexpressed and is associated with fatal disease progression of various cancers." (PMID 40149317, 2025). "B7-H6, also known as NCR3LG1, binds to the NKP30 receptor and activates NK cells, and causes tumor cell lysis." (PMID 35684481, 2022). "In silico analysis of transcriptional data from TCGA datasets (PanCancer Atlas) derived from cancer patients shows that HER2 (ERBB2) and B7H6 (NCR3LG1) transcripts are expressed in different tumor entities." (PMID 35036073, 2021). "NCR3LG1 could be detected on monocytes and neutrophils after application of inflammatory stimuli, and it was initially described as a tumor cell–expressed ligand of NKp30, which is found to be implicated in RA-associated inflammation." (PMID 29340042, 2017). "We focused on homologue 6 (B7H6), also known as natural killer cell cytotoxicity receptor 3 ligand 1 (NCR3LG1), because it was newly discovered and found on several types of tumor cells." (PMID 35311080, 2022). "Another possible biomarker could be B7-H6 (NCR3LG1), which is a novel ligand from the B7 family that is not present in human normal tissues, but is only present in tumor tissues." (PMID 34948300, 2021).
cancer (49 papers, 2013 to 2025). A tumor composed of atypical neoplastic, often pleomorphic cells that invade other tissues. "Cellular heparin or heparin sulfate proteoglycans, which are expressed at high levels on cancer cells, are ligands for all NCRs, while natural killer cell cytotoxicity receptor 3 ligand 1 (B7-H6) and BCL2-associated athanogene 6 (BAT3) are specific ligands for NKp30." (PMID 24138752, 2013). "Conversely, NCR3LG1 has primarily been associated with various cancer types, while RP1-239B22.5 has received minimal research attention—only one study to date has reported elevated expression in late-stage cancer." (PMID 40245477, 2025). "In these orthogonal studies, cancer cells sensitive to NK cells exhibit a “mesenchymal like” transcriptional program: high transcriptional characteristics of chromatin remodeling complex, enhanced expression of B7-H6 (NCR3LG1), and reduced expression of HLA-E/antigen presenting gene." (PMID 37427373, 2023). "In these experiments, B7H6 (NCR3LG1) transcript levels in MNs were high, approximately 5-fold higher compared to the B7H6-positive control cancer cell line HCT15." (PMID 39708357, 2025).
NCR3LG1 also shares sentences with these, for which no sentence is quoted: melanoma (15 papers); lymphoma (14); neuroblastoma (13); hepatocellular carcinoma (10); B-cell lymphomas (6); cervical cancer (6); infection (6); viral infection (6); leukemia (5); HCMV infection (4); non-small cell lung carcinoma (4); acute promyelocytic leukemia (3); atopic dermatitis (3); lung carcinoma (3); pancreatic cancer (3); Sepsis (3); adenocarcinoma of the cervix (2); astrocytoma (2); chordoma (2); myeloid leukemia (2); non-Hodgkin lymphoma (2); prostate carcinoma (2); sarcoma (2); T-lymphoblastic lymphoma (2); triple-negative breast carcinoma (2); acute monocytic leukemia (1); acute myeloid leukemia (1); acute-on-chronic liver failure (1); atherosclerosis (1); autoimmune disease (1).
A further 29 diseases each share a sentence with NCR3LG1 in 1 paper.